HOTTIP (HOXA distal transcript antisense RNA)
Diseases named in the same sentence as HOTTIP in open-access papers (continued):
Sharing a sentence is not in itself a finding about the gene and the disease.
tumor (continued). "In addition, Zhao el al demonstrated that the expression level of lncRNA HOTTIP is significantly correlated with invasion depth, tumor‐node‐metastasis (TNM) stage, and overall survival of GC patients, functioning as an independent prognostic factor." (PMID 34766148, 2021). "Furthermore, we found that the tumor of patients with higher HOTTIP expression tends to be larger in size and to metastasize to distant organs, and the patients with a higher tumor grade and stage." (PMID 32566641, 2020). "The tumor-promoting effect of lncRNA HOTTIP in CRC has been demonstrated by many experiments." (PMID 30940774, 2019). "HOTTIP has been related to tumor metastasis through induction of epithelial-mesenchymal transition." (PMID 30819158, 2019). "Higher expression of HOTTIP was obtained in 39 cases of tumor group (78%), individually." (PMID 32587834, 2019). "HOTTIP was noted to promote the expression of IL-6 by binding to c-jun, which resulted in a promoted PD-L1 expression in neutrophils and immune escape while inhibiting T cell proliferation as well as tumor immunotherapy." (PMID 31533774, 2019). "The ability of HOTTIP to confer chemoresistance was further examined using an in vivo tumor model." (PMID 29367594, 2018). "For this phenomenon, we hypothesized that, tumor-bearing mice may be tolerated in response to the intermittent administration of chemotherapy, and the expression of HOTTIP and HOXA13 in the tumors showed a corresponding increase." (PMID 29367594, 2018). "Therefore, HOTTIP has been considered as a carcinogenic factor, and overexpression of HOTTIP has been reported to promote tumor growth." (PMID 28938659, 2017). "Thirdly, further mechanistic investigations showed that HOTTIP might function as a role of ceRNA by binding miR-574-5p and abrogating their tumor suppressive function in this setting." (PMID 29041935, 2017). "Furthermore, elevated HOTTIP expression level was predominantly found in late-stage tumor tissues and positively correlated with tumor size." (PMID 27806322, 2016). "Compared with adjacent non-tumor tissues, HOTTIP was up-regulated in most PDAC tissues." (PMID 25889214, 2015). "Moreover, like HOTAIR, knockdown of HOTTIP in L3.6pL cells which were used in a xenograft model in athymic nude mice decreased tumor growth and tumor weights compared to tumors in cells expressing HOTTIP (transfected with a non-specific oligonucleotide)." (PMID 25912306, 2015). "Furthermore, combined treatment with gemcitabine and HOTTIP knockdown (n = 4) led to an even further reduction in tumor volume (107 ± 34.31 mm3)." (PMID 25889214, 2015). "We wondered whether the Wnt/β-catenin signal participated in the HOTTIP-mediated HCC tumor growth." (PMID 38481876, 2024). "Based on these results, HOTTIP might have a tumor-promoting role in NPC." (PMID 39049088, 2024). "Since EV cargo contains long non-coding RNAs (lncRNAs), we aimed to analyze whether the oncogenic lncRNA HOTTIP, which higher expression in tumor tissue was related to worse outcome in NSCLC, could be detected in EV from NSCLC patients and serve as recurrence biomarker." (PMID 34111710, 2021). "Moreover, it has been described that HOTTIP levels are related to smoking history in tumor tissue." (PMID 34111710, 2021). "To confirm whether HOTTIP was clinically relevant to human CRC development, we extracted RNA from the plasma and tissues of patients with CRC and found a positive correlation between HOTTIP expression in tumor tissues and that in the plasma of patients with CRC." (PMID 33585440, 2020). "However, lncRNA HOTTIP was highly expressed in tumor tissues compared with adjacent normal tissues." (PMID 31681590, 2019). "Results showed that HOTTIP along with HOXA10 was upregulated in HNSCC cell lines and tumor samples, while miR195 was downregulated in HNSCC cell lines and tumor samples, which indicated that HOTTIP might increase HOXA10 expression through downregulating miR195." (PMID 31032351, 2019).
tumor (continued). "Moreover, HOTTIP knockdown could impair cell proliferation, affect the cell cycle and inhibit tumor growth of mice, while HOTTIP overexpression might enhance cell proliferation and cell cycle in vitro and in vivo." (PMID 29041935, 2017). "Interestingly, the knockdown of HOTTIP in vivo inhibited the growth of the tumor, suggesting that HOTTIP may be a good candidate for therapy of CRC." (PMID 27148353, 2016). "In the literature, there are several works that exploit the properties of HOTTIP, such as its stability in serum and the high expression levels in HCC patients compared to healthy controls, to evaluate a possible role as a tumor marker." (PMID 40284466, 2025). "HOTTIP acts as a ceRNA by sponging miR-218 while FGD5-AS1 sponges miR-195, two microRNAs known for its tumor-suppressive function." (PMID 40781643, 2025). "By sequestering miR-218 and miR-195, HOTTIP and FGD5-AS1 promote tumor cell proliferation, migration, and invasion." (PMID 40781643, 2025). "One study showed that lncRNA HOTTIP promotes hypoxia-induced glycolysis through targeting miR-615-3p/HMGB3 axis thus controls cell division and facilitates tumor cells’ avoidance of apoptosis." (PMID 40616679, 2025). "In the current study, it was revealed that HOTTIP expression was notably elevated in NPC tissues and it was positively related to local tumor invasion, clinical stage, and lymph node metastasis." (PMID 39049088, 2024). "Student’s ttest also showed a statistically significant difference in the expression level of HOTTIP and HOXA13 between tumor tissues and normal tissues." (PMID 37392284, 2023). "LncRNAs regulate EMT process by targeting EMT-related signalling pathways directly (i.e., H19, HOTAIR, ZEB2-AS1, LincRNA-p21 and SNHG1), or function as ceRNAs (i.e., H19, HOTTIP, MALAT1, SNHG1 and SNHG6) for tumour suppressive miRNAs." (PMID 36310592, 2022). "The upregulated circRTN4 promotes tumor growth and liver metastasis in PDAC through the novel circRTN4-miR-497-5p-HOTTIP pathway." (PMID 34983537, 2022). "In their study, HOTTIP was shown to be upregulated in RCC tissue, and the overexpression of HOTTIP was reported to promote RCC proliferation, migration, and invasion in vitro, implicating a tumor-suppressive role of miR-615-3p." (PMID 33042985, 2020). "Kruskal–Wallis test analysis showed that the levels of HOTTIP and KPNA3 in the tumor tissues of patients with recurrent CRC who received mitomycin treatment were higher than those in tumor tissues of patients with primary CRC." (PMID 33585440, 2020). "Regarding HOTTIP, 4 tumor cell lines (HA22T/VGH, HuH6, ACHN and Caki-1) among the ones tested expressed appreciable levels of this lncRNA and in which HOTTIP was significantly down-regulated following treatment with sorafenib." (PMID 31235746, 2019). "In addition, we found that the HOTTIP knockdown could inhibit the expression of EZH1 protein in the mouse xenograft tissues except for its antagonistic effect on tumor growth, which also confirmed that the mechanism of HOTTIP involved in SCLC development possibly through positively regulating EZH1." (PMID 29041935, 2017). "HOTTIP recruits histone-modifying enzymes to activate HOX gene transcription and inhibit tumor-suppressor gene expression." (PMID 28938659, 2017). "We revealed that miR-204 suppresses oncogene HOTTIP expression in HCC, which is consistent with its tumor suppressor role in other malignancies." (PMID 26710269, 2015). "In patients without vascular invasion, HOTTIP expression was linked to TNM stage and tumor differentiation." (PMID 40624028, 2025). "HOTTIP is a lncRNA that is transcribed from the 5’ end of HOXA cluster, involved in the HOX gene network, and can influence cell function by targeting HOXA gene transcription, resulting in epigenetic alteration and promoting tumor occurrence and progression." (PMID 39049088, 2024).
tumor (continued). "Our research team speculated that this might be related to the reduced tumor burden in NPC patients and thus that monitoring serum HOTTIP levels is helpful for evaluating the treatment effect of NPC patients." (PMID 39500018, 2024). "Furthermore, HOTTIP upregulates insulin-like growth factor-2 (IGF-2), which has a role in tumor progression." (PMID 36770654, 2023). "The tumour volumes of the said groups were much lower: by the 20th day, the CSC-induced tumours reached a volume close to 600 mm3, while the volumes of tumours induced by cells with blocked HOXA and HOTTIP were almost zero." (PMID 37108193, 2023). "Due to the great potential of M1 exosomes in tumor treatment and the gap between M1 exosomes or HOTTIP and HNSCC research, this study attempts to explore the function and clarify the mechanism of M1 exosomal HOTTIP in HNSCC." (PMID 35210436, 2022). "In conrast to HOTTIP, HNF1A1/AS1 was found to sponge another tumor suppressive microRNA, miR-34b." (PMID 33920605, 2021). "Serum small EV‐derived MALAT1, DLEU2, HOTTIP, and SNHG1 were significantly highly expressed in patients with HCC and showed good to excellent discriminating capacity that was significantly higher than that of the traditional tumor marker AFP." (PMID 34185961, 2021). "Here, we summarize ncRNAs with tumor-promoting functions: HOTAIR, HOTTIP, MALAT1, lncRNA H19, lncRNA PVT1, circ-RNA ciRS-7, circ-0030235, circ-RNA_100782, circ-LDLRAD3, circ-0007534, circRHOT1, circZMYM2, circ-IARS, circ-RNA PDE8A, miR-21, miR-155, miR-221/222, miR-196b, miR-10a." (PMID 32257946, 2020). "Our study did not prove any significant statistical relationship between HOTTIP expression and clinical and pathological data, especially tumor stage and size." (PMID 32587834, 2019). "To provide evidence for the possible ceRNA regulatory mechanism of HOTTIP, we performed a pilot study on the HOTTIP-miRNA-mRNA network by detecting the expression pattern of HOTTIP-miR195-5p-HOXA10 in HNSCC cell lines and tumor samples in comparison to normal cell lines and normal tissues." (PMID 31032351, 2019). "Compared with the control group, HOTTIP knockdown resulted in a smaller size of the subcutaneous tumor in mice, and intraperitoneal injection of CDDP + VP-16 into the mice with HOTTIP knockdown further inhibited the growth of the tumor." (PMID 29367594, 2018). "Moreover, mechanistic investigations showed that HOTTIP functioned as an oncogene in SCLC progression by binding miR-216a and abrogating its tumor-suppressive function in this setting." (PMID 29367594, 2018). "Additionally, lncRNA growth-arrest-specific 5 (GAS5) plays tumor-suppressive roles in PC cells, whereas NEAT1, MALAT1, HOTTIP and HOTAIR exert oncogenic roles in PC cells." (PMID 29137412, 2017). "Six MLLT1-mutant tumours and six randomly selected MLLT1-wild-type FHWTs were analysed by quantitative reverse transcription PCR, which confirmed increased expression of both HOXA13 and HOTTIP in MLLT1-mutant tumours." (PMID 26635203, 2015). "M1-derived EVs and their key molecule HOTTIP inhibit the progression of HNSCC by competitively binding to miR-5a-19p and miR-3b-19p to up-regulate TLR5/NF-κB signaling pathway, and M1-derived EVs and HOTTIP can polarize monocytes into anti-tumor M1 type, providing new insights into the treatment." (PMID 39165926, 2024). "As for OV, previous studies indicated that regulation of PRGs, including HOTTIP, α-NETA, and LncRNA GAS5 in tumor cells could promote pyroptosis by inducing inflammasome formation, in order to inhibit OV progression, which could be used as a potential target for tumor therapy." (PMID 37730669, 2023). "Finally, in order to determine whether HOTTIP affected the in vivo chemosensitivity, HCT116Mito and HCT116-derived EVs were injected into tumor-bearing nude mice." (PMID 33585440, 2020).
tumor (continued). "Moreover, enhanced HOTTIP has been observed to elevate PD-L1 expression and result in increased immunosuppression, as demonstrated by suppressed T cell proliferation, IFN-γ expression as well as elevated tumor weigh in nude mice." (PMID 31533774, 2019). "However, the later study indicate no relevance of HOTTIP dysregulation to the site and grade of the tumor, lymph nodes metastasis, gender and age." (PMID 32587834, 2019). "Furthermore, HOTTIP expression was significantly associated with several clinical pathological features such as TNM stage (P<0.001) and tumor size (P=0.016), but not with age." (PMID 29884766, 2018). "Finally, the findings presented in this study have allowed us to conclude that HOTTIP overexpression represents a novel biomarker of poor prognosis in SCLC, and may confer multiple properties required for tumor progression and chemoresistant phenotype." (PMID 29367594, 2018). "Furthermore, the expression of HOTTIP was markedly elevated in NPC tissues with III + IV clinical stage, T3 + T4 local tumor invasion, and N2 + N3 lymph node status than those with I + II clinical stage, T1 + T2 local tumor invasion, and N0 + N1 lymph node status (all p < 0.05)." (PMID 39049088, 2024). "The lncRNA expression profiling of this dataset in tumor tissues of CRC responders and non-responders revealed that HOTTIP was expressed at a higher level in the preoperative chemoradiotherapy non-responder group as compared to the responder group." (PMID 33585440, 2020). "The coordinated dysregulation of HOTTIP and HOXA13 in different tumor types supports their strong interaction and involvement in general mechanisms of neoplastic transformation, regardless of specific tumor phenotypes." (PMID 31137568, 2019). "The high expression of HOTTIP is seen in OSCC patients (tongue) with a T3/T4 grade tumour, distant metastasis, or in patients in clinical stages III-IV vs. a low expression in patients with T1/T2 grade tumours and with no distant metastasis or in patients in clinical stages I-II." (PMID 36428681, 2022). "Moreover, univariate analysis of OS and DFS revealed that HOTTIP overexpression was an unfavorable prognostic factor in BC patients (OS, P=0.002; DFS, P<0.001), regardless of other clinicopathological features, such as tumor size, lymph node metastasis, TNM stage, Her-2 status." (PMID 28036281, 2017).
infection (2 papers, 2017 to 2022). The state of being infected such as from the introduction of a foreign agent such as serum, vaccine, antigenic substance or organism. "HOTTIP was stably depleted in PAARH overexpressed SNU-398 cells via infection of HOTTIP specific shRNA lentiviruses." (PMID 35110549, 2022). "To comprehensively investigate the role of HOTTIP in SCLC progression, we additionally established stable HOTTIP knockdown H146 and H446AR cell lines by lentivirus infection." (PMID 29041935, 2017).
adenocarcinoma (1 paper, 2019). A common cancer characterized by the presence of malignant glandular cells. "HOTTIP was validated as a prognostic marker for OS in the TCGA adenocarcinoma cohort (p = 0.025)." (PMID 30819158, 2019). "Finally, since regulatory interactions between lncRNAs, mRNAs and miRNAs have been described, we explored a possible association between the mRNAs and miRNAs whose expression correlated with HOTTIP according to TGCA data on adenocarcinoma NSCLC analyzed with TANRIC." (PMID 30819158, 2019).
respiratory diseases (1 paper, 2024). "Furthermore, dysregulated HOTTIP has been reported in respiratory diseases." (PMID 38238652, 2024).
HOTTIP also shares sentences with these, for which no sentence is quoted: tongue squamous cell carcinoma (3 papers); liver diseases (2); acute lung injury (1); Azoospermia (1); Chronic Myeloid Leukemia (1); colon adenocarcinoma (1); colon cancer (1); glioblastoma (1); lung disease (1); lymphocytic leukemia (1); malignant glioma (1); myeloid leukemia (1); narcolepsy (1); paraganglioma (1); Parkinson’s (1); pheochromocytoma (1); preeclampsia (1); pulmonary fibrosis (1); rectal cancer (1); rectum adenocarcinoma (1); retinopathy of prematurity (1); stomach adenocarcinoma (1); uveal melanoma (1).